CARM1 (coactivator associated arginine methyltransferase 1)
Diseases named in the same sentence as CARM1 in open-access papers (continued):
Sharing a sentence is not in itself a finding about the gene and the disease.
Fibroadenoma (1 paper, 2015). A benign tumor of the breast characterized by the presence of stromal and epithelial elements. "We additionally examined CARM1 protein expression in fibroadenoma and invasive lobular carcinoma breast tissue samples representing benign and cancer tissues respectively using immunohistochemistry." (PMID 26030442, 2015). "Cancer samples did not have significantly higher expression of CARM1FL or CARM1ΔE15 mRNA compared to benign fibroadenomas (p = 0.21 and p = 0.31, respectively), even when stratified by hormone receptor status (p = 0.39, p = 0.30, p = 0.308, for CARM1FL, CARM1ΔE15, and total CARM1, respectively)." (PMID 26030442, 2015).
glycogen storage diseases (1 paper, 2025). "In metabolism, CARM1 specifically regulates the expression of key genes involved in glycogen metabolism, with its dysregulation linked to glycogen storage diseases." (PMID 41488004, 2025).
laryngeal carcinoma (1 paper, 2022). Carcinoma that arises from the laryngeal epithelium. "It plays an oncogenic role enhancing laryngeal cancer cell migration, tumor sphere formation, and tumor growth by regulating CARM1/Sox-2 axis." (PMID 35406495, 2022).
mesenchymal tumours (1 paper, 2025). "They found that the proximal PolyA selection of CARM1, through loss of miRNA binding, upregulates CARM1's EMT inducers and releases miRNAs that downregulate the EMT inhibitor RBM47, serving as a pathological biomarker for mesenchymal tumours and tumour metastasis." (PMID 39964832, 2025).
multiple sclerosis (1 paper, 2017). A progressive autoimmune disorder affecting the central nervous system resulting in demyelination. "Also, given its prominence in the structures observed in this study, R17, while unmodified here, is also the target of methylation by CARM1, while deamination of R17 (together with R2 and R26) by PAD4 also plays a role in the development of multiple sclerosis." (PMID 28353152, 2017).
myeloid leukemia (1 paper, 2024). A clonal proliferation of myeloid cells and their precursors in the bone marrow, peripheral blood, and spleen. "While evaluating the therapeutic relevance of CARM1 inhibition, we observed the differential sensitivity of AML cell lines and noticed that JAK2-V617F mutation-positive myeloid leukemia cells showed a lower sensitivity to CARM1-inhibition." (PMID 38649367, 2024). "We then compared the level of CARM1 protein expression and CARM1-Y149 and -Y334 phosphorylation in 14 myeloid leukemia cell lines, using normal human CD34+ cord blood (CB) cells as control." (PMID 38649367, 2024). "The dependency of JAK2-V617F mutant AML cells on CARM1 is consistent with our previous studies showing that CARM1 is an essential gene for the growth of myeloid leukemia cells." (PMID 38649367, 2024).
myeloid neoplasm (1 paper, 2024). Proliferation of myeloid cells originating from a primitive stem cell. "In certain settings, for example in cells with high levels of phospho-JAK2, CARM1 phosphorylation appears to be required for maximal proliferation of myeloid neoplasms." (PMID 38649367, 2024). "To confirm the clinical relevance of CARM1 phosphorylation, we examined myeloid cells from patients with various myeloid malignancies." (PMID 38649367, 2024).
myocardial infarction (1 paper, 2021). Gross necrosis of the myocardium, as a result of interruption of the blood supply to the area, as in coronary thrombosis. "CARM1, also known as PRMT4, has previously been implicated in myocardial infarction and apoptosis in mice." (PMID 33554857, 2021).
oral squamous cell carcinoma (1 paper, 2022). "CARM1-silencing in oral squamous cell carcinoma cells effectively suppresses tumor invasion." (PMID 36092911, 2022).
osteoarthritis (1 paper, 2025). A noninflammatory degenerative joint disease occurring chiefly in older persons, characterized by degeneration of the articular cartilage, hypertrophy of bone at the margins and changes in the synovial membrane. "This study investigates the role and mechanism of Coactivator Associated Arginine Methyltransferase 1 (CARM1) in osteoarthritis (OA)." (PMID 40611524, 2025). "The authors' research shows that CARM1 regulates cartilage degeneration in osteoarthritis through the ERK1/2 signaling pathway, suggesting its potential as a therapeutic target and providing valuable insights into the mechanisms of cartilage degradation and inflammation in the disease." (PMID 40611524, 2025).
pneumonia (1 paper, 2021). An acute, acute and chronic, or chronic inflammation focally or diffusely affecting the lung parenchyma, caused by an infection in one or both of the lungs (by bacteria, viruses, fungi, or mycoplasma.). "In this study, we report that a chromatin modulator protein arginine N-methyltransferase 4/coactivator-associated arginine methyltransferase 1 (PRMT4/CARM1) is elevated in human lung tissues with pneumonia and in experimental lung injury models." (PMID 34480022, 2021).
rectum cancer (1 paper, 2024). "To clarify whether CARM1 exerts tumorigenic effect on other cancers, we analyzed carcinoma samples from cerebrum, esophagus, liver, lymph, ovary, pancreas, prostate, and rectum cancer patients (n ≥ 15 for each cancer type paired with adjacent normal tissues)." (PMID 38476024, 2024).
sarcoma (1 paper, 2022). A usually aggressive malignant neoplasm of the soft tissue or bone. "As for MSI, CARM1 expression is also positively correlated with LUAD (P = 0.022), LUSC (P = 0.00028), SARC (sarcoma, P = 0.0029), STAD (P = 0.017) and UVM (P = 0.014), but is negatively correlated with that of SKCM (P = 0.0038), HNSC (P = 0.0022), READ (P = 1.3e-07) and DLBC (P = 0.0044)." (PMID 35033016, 2022).
spina bifida (1 paper, 2010). A congenital neural tube defect in which vertebrae are not fully formed. "The purpose of this study is to evaluate the potential association between variations among human CITED2, CREBBP, EP300, TFAP2A, CARM1 and ALX1 genes and the risk for spina bifida." (PMID 20932315, 2010). "We have observed modest associations with risk of spina bifida in CITED2, EP300, CREBBP, TFAP2A and CARM1 genes but not ALX1 gene." (PMID 20932315, 2010).
steatosis (1 paper, 2024). Increased lipid within the cytoplasm of cells. "CARM1 has long been documented to play key roles in maintaining/disrupting hepatic homeostasis by regulating gluconeogenesis, hepatocellular carcinogenesis, and steatosis." (PMID 39603205, 2024).
testicular seminoma (1 paper, 2022). A malignant germ cell tumor arising from the testis. "CDKN2AIP induces testicular seminoma cell senescence by suppressing CARM1 expression and eIF4β phosphorylation." (PMID 35593475, 2022). "Meanwhile, CARM1 may also serve as potential therapeutic target for future testicular seminoma treatment." (PMID 35593475, 2022). "In summary, through clinical samples combined within vitro tumor cell line and mouse xenograft model experiments, we demonstrated for the first time that CDKN2AIP induces testicular seminoma cell senescence and suppresses CARM1 expression and eIF4β phosphorylation." (PMID 35593475, 2022).
type 2 diabetes (1 paper, 2022). "A study had shown that CARM1 expression was significantly increased in type 2 diabetes, which might play a vital role in diabetes-related diseases." (PMID 35096421, 2022).
uterine corpus endometrial carcinoma (1 paper, 2021). A endometrial carcinoma (disease) that involves the body of uterus. "Uterine corpus endometrial carcinoma (UCES) samples had the highest CARM1 mutation frequency of all cancer types." (PMID 34745258, 2021).
uveal melanoma (1 paper, 2022). A melanoma derived from melanocytes of the uveal tract. "Analysis results of DFS presented a correlation between high CARM1 expression and poor prognosis of ACC (P = 0.00011), BLCA (P = 0.0012), LGG (P = 0.034), MESO (P = 0.012), UCS (P = 0.029) and UVM (uveal melanoma, P = 0.021)." (PMID 35033016, 2022).
cancer (109 papers, 2009 to 2026). A tumor composed of atypical neoplastic, often pleomorphic cells that invade other tissues. "The enzyme coactivator-associated arginine methyltransferase 1 (CARM1) is highly expressed in different types of cancer." (PMID 40016178, 2025). "The protein arginine methyltransferase, CARM1 (coactivator associated arginine methyltransferase 1), is emerging as a potential cancer therapy target and inhibitors have been developed." (PMID 40123976, 2025). "Studies have identified abnormal expressions of PRMT3 and CARM1 in several malignancies, closely linked to cancer progression, advancement, and resistance to treatment." (PMID 39964832, 2025). "Aberrant expression and/or activation of CARM1 has been linked to a variety of human diseases, particularly cancers, such as breast, prostate, colorectal, lung and liver cancers." (PMID 38676947, 2024). "The blockade of CARM1 facilitates ferroptosis and effectively enhances ferroptosis‐associated cancer immunotherapy." (PMID 37946697, 2023). "The inhibition of PRMT5 as well as PRMT1 and CARM1 have been shown to cause splicing inhibition and display anti-cancer properties in several cancers." (PMID 37568815, 2023). "We will start by highlighting what is known about the normal roles of CARM1 with respect to in vivo mouse models, CARM1 substrates that are implicated in transformation and cancer and CARM1-related preclinical studies." (PMID 37536629, 2023). "Inhibition of the IRE1α/XBP1s branch alone or in combination with immune checkpoint blockade provides a therapeutic strategy for several cancer types with frequent coactivator-associated arginine methyltransferase 1 (CARM1) overexpression, including OC44." (PMID 37817482, 2023). "Protein arginine methyltransferase 4 (PRMT4), also known as coactivator-associated arginine methyltransferase 1 (CARM1), has a carcinogenic role in human cancer and is closely involved in the process of tumor growth and immune tolerance." (PMID 36713412, 2022). "The aberrant expressionof CARM1 has been linked to a variety ofdisease states, most prominently in the field of cancer." (PMID 35579944, 2022). "CARM1 expression, for example, was found to be substantially correlated with cancer-associated fibroblasts and CD8+ T cells." (PMID 34745258, 2021). "Cellular or animal-based evidence has suggested an association between coactivator-linked arginine methyltransferase 1 (CARM1) and cancer progression." (PMID 34745258, 2021). "For instance, the degree of CARM1 expression in PRAD was found to be negatively linked with the immune infiltration level of fibroblasts (cancer-linked) using the XCELL algorithm (Rho = −0.13, P = 7.99e − 03)." (PMID 34745258, 2021). "Global profiling of CARM1 substrates revealed that chromatin regulators and RNA processing proteins are CARM1 substrates, uncovering novel cancer susceptibilities and therapeutic vulnerabilities to CARM1 inhibition." (PMID 34865122, 2021). "In many forms of cancer, the heatmap data revealed a positive link between CARM1 and the underlined five genes." (PMID 34745258, 2021). "GAPDH is also one of the targets for modification during cancer reprogramming such as the methylation directed by coactivator-associated arginine methyltransferase 1 (CARM1 or PRMT4)." (PMID 32161720, 2020). "The requirement of CARM1 is implicated in multiple cancers, with its methyltransferase activity particularly addicted by hematopoietic malignancies and metastatic breast cancer." (PMID 31657716, 2019). "This implied that NAC1 is a gene-specific transcription factor and the interacting partner CARM1 functions as a coactivator together with the p160 family of nuclear receptor-associated proteins in cancer cells." (PMID 29983869, 2018).
cancer (continued). "Together, identification of many cancer-relevant substrates across diverse biological pathways and the elevated mutation rate at, or near, CARM1-methylated arginines underscore the significance of substrate methylation by CARM1 in oncogenic processes." (PMID 28537268, 2017). "COSMIC analysis also reveals that 17 of the putative CARM1 substrates are causally implemented in cancer pathogenesis." (PMID 28537268, 2017). "Both CARM1-methylated arginines and the surrounding recognition sequences were frequently targeted by somatic mutations in cancer, likely inducing reduction or complete abolishment of methylation by CARM1." (PMID 28537268, 2017). "Notably, favorable interactions were identified with PPARG and CARM1, supporting therapeutic relevance in inflammation and cancer, alongside additional targets associated with neurodegeneration and bone metabolism." (PMID 42075901, 2026). "A higher tumor grade and advanced cancer stage were associated with higher expression of CARM1." (PMID 40016178, 2025). "Overexpression of CARM1 is closely associated with the occurrence of various cancers." (PMID 39964832, 2025). "Further research into the regulatory mechanisms underlying the CARM1-PI3KC2α axis in microtubule dynamics may provide novel therapeutic strategies for improving cancer treatment efficacy while minimizing adverse effects." (PMID 40045375, 2025). "MED12 is frequently mutated in human cancers, and these tumor suppressor functions might be augmented by its association with CARM1." (PMID 37536629, 2023). "CARM1, a member of the protein arginine methyltransferase family, is a coactivator of many tumor-associated transcription factors and is abnormally expressed in many cancers." (PMID 35096421, 2022). "Moreover, the potential association between CARM1 genetic alterations and clinical prognosis was analyzed in various cancers cases." (PMID 35033016, 2022). "Since both these metabolic pathways promote cell proliferation in multiple cancers, they could contribute to molecular mechanisms associated with the effects of CARM1 in the cell proliferation of these tumors." (PMID 35274101, 2022). "Therefore, several algorithms were applied to investigate the relationship between CARM1 expression and cancer-associated fibroblasts infiltration." (PMID 35033016, 2022). "Mounting evidence indicates that CARM1 is associated with carcinoma metastasis." (PMID 36092911, 2022). "CARM1 expression was significantly varied in distinct molecular subtypes in most cancer types, suggesting that CARM1 might be a promising diagnostic pancancer biomarker as suggested by these findings." (PMID 34745258, 2021). "However, the role of CARM1 and the associated therapeutic vulnerabilities conferred by its expression in cancers including EOC remain to be explored." (PMID 34493732, 2021). "Furthermore, in various TCGA human cancers, a positive association was found between CARM1 copy number and mRNA expression." (PMID 34745258, 2021). "The impact of GAPDH on the efficacy of metabolism in cancer cells may be also regulated by the coactivator-associated arginine methyltransferase 1 (CARM1 or PRMT4), an enzyme methylating arginine-234 on the GAPDH molecule." (PMID 32370188, 2020). "Protein arginine methyltransferase (PRMT) 4 (also known as coactivator-associated arginine methyltransferase 1; CARM1) is involved in a variety of biological processes and is considered as a candidate oncogene owing to its overexpression in several types of cancer." (PMID 29719619, 2018). "This significant enrichment (Fisher's exact test P values of 5.6e–31 and 7.8e–24) indicates that CARM1 methylation sites and recognition sequences are vulnerable to mutation in cancers and may provide a functional advantage." (PMID 28537268, 2017). "CARM1, a member of PRMTs, has been implicated in a variety of cancers." (PMID 27872854, 2016).
cancer (continued). "Furthermore, cellular studies revealed that both inhibitors exhibited antiproliferation activity in several CARM1-associated cancer cell lines." (PMID 27872854, 2016). "The central position occupied by OCT4, SOX2, and CARM1 in the control of pluripotency in undifferentiated cells may point the way to valuable opportunities to disrupt cell phenotypes associated with the survival and proliferation of cancer stem cells." (PMID 35274101, 2022). "CARM1 is frequently overexpressed in various cancers and exists in multiple alternatively spliced isoforms, each of which exhibits distinct biological properties." (PMID 41152553, 2025). "Significantly, alterations in CARM1 expression, primarily characterized by up‐regulation, have been consistently documented in numerous human cancer types." (PMID 40611524, 2025). "Among all cancer types, the role of CARM1 in ER‐positive breast cancer has been the most extensively studied." (PMID 39964832, 2025). "Numerous studies have shown that PRMT3 and CARM1 are overexpressed or dysregulated in cancer, hence the development of potent and selective inhibitors against PRMT3 and CARM1 has attracted widespread attention." (PMID 39964832, 2025). "Data from the DepMap database suggest that IKZF3 and CARM1 are independent dependencies in MM cells and that they are uniquely different from other cancers." (PMID 40123976, 2025). "For instance, the CARM1 protein plays a multifaceted role in cancer metabolism, affecting metabolic pathways, regulating gene expression, and promoting metastasis." (PMID 39982908, 2025). "Understanding this complexity is essential for the development of targeted therapeutic strategies and for leveraging CARM1 as a prognostic or predictive biomarker for cancer." (PMID 41152553, 2025). "Prior research has demonstrated the pivotal involvement of CARM1 in the modulation of diverse cellular processes, including RNA processing, transcription activation, tumorigenesis, cancer progression, cell growth, differentiation, and apoptosis." (PMID 40611524, 2025). "As the CARM1–PI3KC2α axis regulates microtubule dynamics, we examined the effects of depleting CARM1 or PI3KC2α on cancer cell proliferation." (PMID 40045375, 2025). "This regulation is especially critical in cancer, where the role of CARM1 extends beyond transcriptional coactivation to include functions such as cytoplasmic scaffolding, mitochondrial dynamics and immune modulation." (PMID 41152553, 2025). "We have shown that disrupting the CARM1–PI3KC2α axis substantially impedes cell cycle progression and impacts microtubule dynamics by arresting in the mitotic stage, effectively inhibiting cancer cell proliferation." (PMID 40045375, 2025). "Recent studies indicate that PRMT3 and CARM1 play significant roles in the occurrence and progression of cancer." (PMID 39964832, 2025). "The development of these inhibitors is grounded in a thorough understanding of PRMT3 and CARM1's mechanisms of action within tumours and an extensive analysis of their expression and functionality across different cancer types." (PMID 39964832, 2025). "Their findings demonstrated that increasing CARM1 levels enhanced the sensitivity of cancer cells to RSV." (PMID 40969596, 2025). "Through regulating autophagy, CARM1 accelerates the G1-S transition, promotes cancer cell growth, and mitigates ER stress-induced apoptosis." (PMID 38619752, 2024). "Coactivator-associated arginine methyltransferase 1 (CARM1), a type I PRMTs, is deregulated in numerous cancers and plays critical roles in cancer progression by catalyzing asymmetric di-methylation of histone or nonhistone substrate proteins." (PMID 39567506, 2024). "This review provides a comprehensive exploration of the various physiological functions of CARM1 in the context of cancer." (PMID 38619752, 2024). "CARM1 also orchestrates remodeling of the metabolic network in cancer cells, adapting them to variable oxidative stress conditions." (PMID 38619752, 2024).